ATG12 (autophagy related 12)
Diseases named in the same sentence as ATG12 in open-access papers (continued):
Sharing a sentence is not in itself a finding about the gene and the disease.
infection (34 papers, 2009 to 2026). The state of being infected such as from the introduction of a foreign agent such as serum, vaccine, antigenic substance or organism. "Contribution of some autophagy-related proteins (ATG16L1, ATG5, and ATG12) in lysosomal exocytosis was recently highlighted in the context of host cell infection by the Gram-positive pathogenic bacterium Listeria monocytogenes." (PMID 35086419, 2022). "We used HRM qRT-PCR to confirm the presence of mutated Atg12 RNA transcripts after the infection with the gRNAs." (PMID 32985978, 2020). "This study showed that liver autophagy-related Beclin1, p62, LC3BII/I, Atg7, and Atg12 levels decreased significantly at two, four, and six weeks post-infection." (PMID 38393131, 2024). "The Lc3b, Beclin1, Atg7, and Atg12 mRNA levels were significantly lower at four and six weeks after infection than those in the uninfected group." (PMID 38393131, 2024). "The mRNA expression levels of Atg12 were 0.66 ± 0.11, 0.38 ± 0.096, and 0.32 ± 0.051, respectively, which were significantly lower than those before infection (1.0 ± 0.15) (F = 51.55, p < 0.01)." (PMID 38393131, 2024). "There were no marked changes noted in the expression of Becn1, Atg5, Atg7, Atg12, Atg16l1 or Atg16l2 both before and 6 h after infection." (PMID 35903351, 2022). "Inhibition of LC3 lipidation in ASFV infected cells is different to that observed after infection by with vaccinia virus where aberrant lipidation of LC3 is promoted by direct conjugation between ATG12 and ATG3." (PMID 34406116, 2021). "Messenger RNA levels of the autophagy-related genes were significantly elevated at most of the timepoints after infection, except for some genes (Bcl-2, Atg5, Atg12, DRAM1, and VMP1) whose transcription levels declined at 7 dpi." (PMID 33600403, 2021). "Accordingly, infection with shPARP1 decreased the autophagy and related gene expression (Gabarapl1, ATG12 and LC3) and raised the expression of p62 in the myocardium, as compared to scrambled shRNA (Scr shRNA)." (PMID 30323296, 2018). "To test the effects of overexpression of CFTR in hepatocytes on the expression of autophagy-related proteins p62, BECN1, LC3, and Atg12, we detected their expression after infection." (PMID 29415998, 2018). "The production of ROS in ATG5 or ATG12 siRNA group was significantly higher than that of control siRNA group upon infection with the F. nucleatum." (PMID 27828984, 2016). "We also investigated the impact of VgrG2 on the mTOR signaling pathway by examining the transcription levels of key genes, including mTOR, ULK1, Beclin-1, P62, LC3, Atg3, Atg5, and Atg12, following infection, and assessed the expression of the autophagy marker protein LC3-II." (PMID 40266908, 2025). "RBAC can also stimulate cytokine secretion in macrophages, especially TNF-α and IL-6, to initiate inflammation during infection and activate autophagy-related proteins (Beclin-1, Atg5, Atg12, Atg16L) for clearing cellular debris and regulating inflammatory responses." (PMID 37687141, 2023). "Our findings strongly recommend that the autophagy-related gene ATG12 inhibits the expression level of vegetative growth and that pathogenicity related genes may regulate the mechanism of infection in F. oxysporum." (PMID 34066497, 2021). "Our results indicate that after the infection autophagic genes [Beclin-1 (p ≤ 0.03), UVRAG (p ≤ 0.03), Atg5 (p ≤ 0.01), Atg12 (p ≤ 0.01) and Atg16L (p ≤ 0.03)] are upregulated in contrast to the control group." (PMID 39845048, 2024). "The expression of ATG5, ATG7, ATG12, and LC3 in BMDMs was remarkably enhanced after both BCG and H37Rv infection." (PMID 38016969, 2023).
infection (continued). "Relative to the expression levels observed at the time of infection (0 h post-infection), the transcripts of MAP1LC3, ATG3, and ATG12 were upregulated at 24 h post-infection and returned to basal level by 48 h post-infection." (PMID 36298785, 2022). "Our RT-qPCR results showed that infection with H. pylori decreased the expression of the autophagy genes (Beclin1, ATG5, and ATG12 expression decreased by 0.71-, 0.73-, and 0.68-fold, respectively) compared to the negative control group (1-fold)." (PMID 36139826, 2022). "First, monitoring of autophagic flux following infection revealed a marked reduction of Atg7 and LC3B expression profile and low accumulation levels of autophagy-related LC3-I, LC3-II, and the Atg12–Atg5 protein complex." (PMID 32064256, 2019). "We found that both Atg12-Atg5 and LC3 were colocalized with Lyn, and were shifted into early phagosome, late phagosome or phagolysosome fractions following infection." (PMID 26735693, 2016). "This notion is supported by evidence showing that intracellular infection with Francisella down-regulates several autophagy-related genes in THP-1 human monocytes, including ATG5, ATG12, ATG16L2, ATG7, ATG4A and class III PI3K." (PMID 20003180, 2009). "We found that the amount of d ATG12 mRNA increased about 3.5-fold by R38AK41A infection but not Beclin-1 mRNA." (PMID 30619194, 2018). "Results showed that infection with Ad-PARP1 resulted in up-regulation of Gabarapl1, ATG12 and LC3." (PMID 30323296, 2018). "Moreover, DENV-ADE infection induced higher ATG5 and ATG12 transcription at very early stage (0.5 and 1 hours post-infection) compared to the DENV direct infection." (PMID 26923481, 2016). "At 6 h post-infection (hpi), the enriched pathways included proteasome, ribosome, and regulation of autophagy, with the core genes of the most significantly enriched pathway in autophagy regulation (FDR = 0.2325) including ATG12, PIK3C3, GABARAPL1, ATG4C, and ATG4A." (PMID 37515115, 2023). "We observed that Lyn could bind well to Atg12-Atg5 and LC3 complex upon Pa infection." (PMID 26735693, 2016). "Huh7 infection by HCVpp was not altered in cells treated with siRNA against LC3, ATG7 or ATG12, thus suggesting that neither LC3 nor the ATG5-12 conjugate is involved in viral entry." (PMID 28067309, 2017). "When one of the proteins (Atg12) responsible for conjugating LC3 into the phagosome was screened, it was diminished in the splenic macrophages from red pulp of the diabetic animals without infection compared to healthy control." (PMID 33312173, 2020). "In addition to its role in the formation of an interferon gamma-inducing conjugate with ATG12 and/or ATG16L in several antiviral responses not related to autophagy machinery engagement (ATG5-ATG12/ATG16L), ATG5 has been found to independently participate in other responses against infection." (PMID 37175443, 2023).
retinopathy (1 paper, 2024). "In this regard, it has been recently reported that the immunoproteasome degrades the autophagy-related proteins ATG5 and ATG12 in cardiomyocyte and retinopathy models, something that could be occurring in the context of hypothalamic neurons." (PMID 39095788, 2024).
ATG12 also shares sentences with these, for which no sentence is quoted: atherosclerosis (3 papers); gallbladder cancer (3); B-cell CLL (2); bacterial infection (2); cardiovascular diseases (2); esophageal cancer (2); fatty liver (2); glioblastoma (2); liver fibrosis (2); renal cell carcinoma (2); adenoma (1); Alzheimer disease (1); Atrophic Gastritis (1); Cerebral ischemia (1); cholangiocarcinoma (1); chronic obstructive pulmonary disease (1); colon adenocarcinoma (1); dengue (1); depression (1); developmental delay (1); dyslipidemia (1); embryonic carcinoma (1); epilepsy (1); gynecological tumor (1); heart failure (1); Hypertension (1); Intellectual disability (1); intestinal inflammation (1); knee osteoarthritis (1); laryngeal squamous cell carcinoma (1).
A further 19 diseases each share a sentence with ATG12 in 1 paper.